CD36 (CD36 molecule (CD36 blood group))
Diseases named in the same sentence as CD36 in open-access papers (continued):
Sharing a sentence is not in itself a finding about the gene and the disease.
tumor (continued). "Collectively, our findings uncover a mechanism by which tumor cells metabolically interact with macrophages in TME, and suggest a therapeutic potential of targeting CD36 as immunotherapy for liver metastasis." (PMID 36184646, 2022). "Intriguingly, both pharmacologically and genetically targeted CD36 of Treg cells specifically induced their intratumoral apoptosis, leading to increased CD8+ T cells infiltration in the tumor and enhanced anti-PD-1 therapeutic effects." (PMID 36275711, 2022). "In summary, CD36 has an important synergistic effect on Treg cells by reprogramming the lipid metabolism of Treg cells to adapt to the TME and promote tumor development." (PMID 36354702, 2022). "On the other hand, cholesterol in the tumor microenvironment promotes CD36-mediated fatty acid uptake in CD8+ T cells, leading to increased ferroptosis in T cells and hence dampened tumor suppression." (PMID 36282248, 2022). "CD36 is also related to endothelial apoptosis via binding to TSP-1, exerting a strong antiangiogenic effect, with significance on tumor progression." (PMID 35054787, 2022). "The model was powered by seven factors: number of positive lymph nodes, age, pT stage, maximum diameter of tumor, Clavien-Dindo classification for complication, expression of CK7 and CD36." (PMID 36090344, 2022). "The expression levels of CD36, PTGR1, SUCLG2 and CPT2 were significantly decreased in tumor tissues." (PMID 36568396, 2022). "Among them, two xenografts (CD36, CD44) were sacrificed before P2 (Covid19 pandemic period) but after reimplantation, a tumor growing on one passage was noted." (PMID 35326637, 2022). "In summary, CD36 regulates lipid uptake and stromal protein production between CAFs and TME and regulates tumor progression." (PMID 36354702, 2022). "In agreement, intratumoral Treg cells upregulate CD36 expression and activate the PPAR-β pathway and lactate metabolism to survive in the tumor microenvironment." (PMID 36568966, 2022). "Meanwhile, lipid staining showed a mass of lipids in obese N + tumor samples, and IHC analysis indicated an increase in LPL and CD36 expression in N + cases, implying a crucial role for exogenous lipid supply in LNM." (PMID 36397145, 2022). "In xenotransplants formed by PC cells with CD36 knockdown, FA uptake from TME is impaired, reducing lipid biosynthesis, activation of oncogenic lipid signaling pathway, and attenuating tumor growth." (PMID 36568966, 2022). "CD36 knockout (KO) mice maintain CD8 T cell polyfunctionality through the co-production of IFN-γ and TNF-α, which abrogates tumor growth." (PMID 34983949, 2022). "Studies have shown that one of the early characteristics of tumor cells is the enhancement of FA biosynthesis, which is mainly manifested by the increased expression of ACC, FASN, CD36, and FABPs." (PMID 35743814, 2022). "The uptake of free FA in BC cells is mediated by several proteins, including CD36, FABPs and CPT1 that enhance tumor progression and aggressiveness." (PMID 36551752, 2022). "In tumor-infiltrating MDSCs, the use of energy is shifted from glycolysis toward FAO, which is characterized by CD36-mediated fatty acid uptake and upregulated expression of FAO enzymes." (PMID 35790992, 2022). "Then, CAF-derived THBS2 binds to its cognate receptors integrin αvβ3/CD36, leading to the activation of MAPK pathway to promote tumor growth." (PMID 35547750, 2022). "With tumor progression, a steady buildup of TME FAs is an environmental cue to the PPARα-mediating FAO upregulation, resulting in the increased fatty acid translocase or CD36 expression on the CD8+ TILs for adaptation to lipid-enriched TME." (PMID 36275711, 2022). "Recently, it has become clear that TAMs accumulate lipids through CD36 and serve as a source of FAO used for differentiation and tumor promotion." (PMID 33514004, 2021). "CD36 overexpression enhanced the proliferation, migration, and invasion of HCC cells in vitro and promotes HCC tumor growth and metastasis in vivo." (PMID 33771982, 2021).
tumor (continued). "The overexpression of CD36 requires STAT3 and STAT5 signalling activation, both of which are triggered by tumour-released G-CSF and GM-CSF." (PMID 34685679, 2021). "In GC cells, fatty acids can upregulate CD36 expression to trigger the epithelial to mesenchymal transition (EMT) process, thereby promoting tumor growth and omental metastasis." (PMID 34459127, 2021). "Inhibition of lipid uptake by genetic depletion of the FA translocase CD36, or inhibition of the STAT3 or STAT5 signal, results in an impaired immunosuppressive function in MDSCs and delayed tumor growth." (PMID 34766135, 2021). "BCSCs with high CD36 and moderate PKD-1 expression were localized outside of the tumor nest and had invaded into the surrounding tissue, whereas the BCSCs with low CD36 and moderate PKD-1 expression appeared to form a vessel-like structure or capillary." (PMID 34168243, 2021). "Transplantation of CD36-null CD8+ T cells resulted inincreased T cell response and reduced tumor growth, compared to CD36+ Tcells." (PMID 34603769, 2021). "As an illustration, CD36 ablation in Treg reduced its survival in TME conditions, leading to tumor growth suppression, antitumor activity enhancement of T cells and additive antitumor responses with anti-PD1 therapy." (PMID 34356862, 2021). "CD36 overexpression promoted the proliferation, migration, invasion, and in vivo tumor growth of HCC cells, whereas silencing CD36 had the opposite effects." (PMID 33771982, 2021). "CD36 has been reported to regulate PI3K/AKT signaling in tumor progression, but the exact interaction between APOC2 and CD36 as well as subsequent effect on PI3K/AKT/mTOR signaling in GC have not been investigated." (PMID 34459127, 2021). "This fatty acids transporter is also important in the presence of tumors by accelerating tumor growth but also inhibits angiogenesis and promotes vascular apoptosis when TSP-1 binds to CD36 on the surface of the MVEC." (PMID 33809784, 2021). "We further verified the potential for CD36 and FABP4 inhibitors (SSO and BMS309403, respectively) to suppress tumour growth through in vivo xenograft nude mice models." (PMID 34561446, 2021). "By integrating proteomic and transcriptomics profiles of GC and PM samples, we reported that APOC2 cooperated with CD36 to regulate EMT process via PI3K/AKT/mTOR signaling, which eventually promoted tumor progression and PM in GC." (PMID 34459127, 2021). "We found that CD36 is highly expressed in HCC and elevated CD36 expression contributes to tumor growth and metastasis in vitro and in vivo." (PMID 33771982, 2021). "Genetic depletion of CD36 or inhibition of STAT3/5 restricted oxidative metabolism and immunosuppressive function in MDSCs, resulting in CD8+ T cell-dependent tumor delay due to reduced ARG1 and iNOS." (PMID 34742349, 2021). "Drivers of this metabolic profile shift include tumor-derived cytokines (e.g., G-CSF and GM-CSF) that signal through STAT3 and STAT5 pathways to upregulate CD36, a fatty acid transporter." (PMID 34988072, 2021). "CD36 attenuates angiogenesis by binding to TSP-1 and thereby inducing apoptosis or blocking the vascular endothelial growth factor receptor 2 pathway in tumor microvascular endothelial cells." (PMID 32781778, 2020). "Pharmacological and shRNA-mediated inhibition of CD36 decreases proliferation of primary CRC cells in vitro and inhibits tumor growth in vivo." (PMID 32850342, 2020). "A further illustration of how the gene expression level changed over time was made for CD36 and CD44 by plotting expression levels measured by NanoString against the time gap between primary and recurrent tumor samples." (PMID 33352957, 2020). "To further analyze CD36 in CRC we analyzed tissues from PDX models, which retain the intratumorally clonal heterogeneity and tumor microenvironment of the parent tumor through passages in mice." (PMID 32850342, 2020).
tumor (continued). "To further establish that CD36 promotes cellular proliferation via upregulation of pro-survival pathways, we utilized a PDX tumor model, Pt 2402, which was established from a CRC metastasis to the lung and is positive for CD36 expression." (PMID 32850342, 2020). "TSP-1 harbors a TSR sequence that can interact with the CLESH domain in CD36, as well as a potential TGF-β activation sequence that plays a critical role in tumor-cell metastasis." (PMID 31410189, 2019). "Immunohistochemistry study revealed that tumour specimens from both oral cavity and peritoneum were negative for tumour necrosis factor alpha and CD24 but positive for CD44 and CD36." (PMID 31645882, 2019). "Immunohistochemistry of serial sections of primary tumor tissue confirmed enhanced PPARγ (green), PTEN (green), and CD36 expression (green) upon ApoSQ injection." (PMID 30842627, 2019). "This study showed that membranous expression of CD36 and FATP4 was higher in RCC tumor tissues than in normal tissues, whereas cytoplasmic ACSL1 was reduced in RCC tumor cells." (PMID 31089396, 2019). "Therefore, reduced CD36 expression might help tumor cells in evading the immune system." (PMID 31410189, 2019). "In this study, we evaluated the differential immunohistochemical expression of fatty acid transporters including CD36, FATP4, and ACSL1 between RCC tumor cells and normal renal tubular epithelial cells." (PMID 31089396, 2019). "Apoptotic tumor cells also release LCFAs and ox-PLs and thus act as carriers of miR-375 for CD36-mediated uptake, and miR-375, in turn, enhances TAM migration and infiltration into tumor spheroids." (PMID 31410189, 2019). "Cancer cells themselves can also alter lipid metabolism, often by upregulating FA receptor CD36 and FAB4 in omental metastases at the tumor/adipocyte interface to promote FA and cholesterol uptake from adipocytes to fuel tumor progression." (PMID 30042343, 2018). "Accordingly, an anticancer drug that can target CD36, TSP-1, and HMGCS2 during tumor treatment has great potential for slowing or blocking tumor metastasis." (PMID 29914089, 2018). "For example MAMPCs expressed mature macrophage markers such as CD14, CD36, CD64, and CD206 at comparable levels with MAMs, suggesting that MAMPCs have committed to a macrophage lineage in the tumor microenvironment." (PMID 29387063, 2017). "Similar to our previous report, this pathway downregulates CD36 expression and promotes arteriolar remodeling in the TME, an essential process for enhancing tumor tissue perfusion and nutrition." (PMID 28186980, 2017). "We confirmed that MAMPCs and MAMs in the metastatic lung expressed significantly higher levels of CD14, CD36, CD64 (Fcgr1), CD206 (Mrc1) and CCR5 proteins compared with circulating C-MOs in the tumor-bearing mice." (PMID 29387063, 2017). "Among TSP-1 ligands, CD36 and CD47 cell-surface receptors act as key integrators of multiple signals regulating tumor growth and dissemination both positively and negatively." (PMID 26578962, 2015). "To verify the association between FA uptake gene expression and EMT observed in TCGA data, we further investigated the protein expression of CD36 and EMT genes in the human HCC tumor samples." (PMID 26424075, 2015). "Inhibition of fatty acid uptake via CD36 blockade or suppression of ATGL-mediated lipolysis restores LDs integrity and rescues cell viability, underscoring BACE2’s role in maintaining a balanced lipid state critical for tumor cell survival and proliferation." (PMID 41507981, 2026). "One study demonstrated that fatty acid uptake, facilitated by the upregulation of CD36 expression in CD8+ T cells within the tumor microenvironment (TME), can trigger the onset of ferroptosis in these T cells, thereby impairing their anti-tumor capacity." (PMID 40006729, 2025).
tumor (continued). "In our study, analysis of the TCGA database and CD36 protein staining on tissue microarrays revealed that CD36 is downregulated in TNBC, with its expression level significantly negatively correlated with the prognosis of this tumor type." (PMID 41267927, 2025). "Lipid metabolism directly regulates glucose utilization: CD36‐mediated fatty acid uptake in TAMs suppresses glycolysis while enhancing OXPHOS, creating an M2‐favoring metabolic state that provides lactate and ketone bodies to fuel neighboring tumor cells." (PMID 40904700, 2025). "For example, selecting patients whose tumour and immune microenvironment show high FAO dependence (via elevated CPT1A, ACAD, or CD36 expression) may maximise benefit while monitoring liver enzymes, lipid profiles, and T cell memory markers may enhance safety." (PMID 41394868, 2025). "Elevated oxLDL levels in MSS CRC contribute to tumor progression and diminish ICI efficacy by modulating metabolic reprogramming and immunosuppressive mechanisms within the tumor microenvironment (TME) by activating receptors such as LOX-1 and CD36." (PMID 40563359, 2025). "In particular, our analysis revealed increased expression of various immune modulatory molecules (CD274 (PD-L1), OSM, PTGES2, CD36, and MSR1) by tumor-infiltrating monocytes and neutrophils suggesting an immune suppressive role is adopted following infiltration into the TME." (PMID 39932553, 2025). "In such a situation, CD36 and FATP could be overexpressed both in normal tissue surrounding the tumor (to export VLCFA) and in tumor tissue (to import VLCFA)." (PMID 40759952, 2025). "CD36 displayed strong positive correlations with immune receptors such as CCR1, CCR2, CCR4, CXCR1, and CXCR2, indicating its potential role in amplifying chemokine-receptor interactions and shaping immune cell trafficking within the tumor microenvironment." (PMID 41550652, 2025). "The differences between tumor and metastatic tissues were gene-specific; for instance, no significant changes were observed in some genes, such as CD36 and ENPEP (p = 0.42), whereas significant changes were detected in others, such as MARCKS (p = 5.40 × 10−7)." (PMID 40565366, 2025). "This suggests that CD36 plays a significant role in the prognosis of TNBC and may function as a tumor suppressor in this cancer subtype." (PMID 41267927, 2025). "CD36 is one such protein that promotes Treg proliferation at the expense of CD8 T cell function through a PPAR-β dependent mechanism increasing lipid peroxidation in CD8 T cells, particularly in the tumor microenvironment (TME)." (PMID 40692789, 2025). "Moreover, extracellular cystine is preferentially taken up by tumour cells that highly express SLC7A11 but affect intratumoural CD8+ T cells function containing compromised GSH synthesis, CD36‐governed ferroptosis occur and exhausted markers expression." (PMID 40045458, 2025). "To assess lipid uptake and CD36 expression, we first digested the tumor tissue using a tumor dissociation kit (Miltenyi Biotec), isolated CD3 cells using a CD3 selection kit (BioLegend), and then stained these isolated CD3 cells with BODIPY 500/510 and CD36." (PMID 39773913, 2025). "In metastatic liver cancer and oral carcinoma, CD36 expression is notably higher than in non-metastatic tumor cells." (PMID 40725201, 2025). "Interestingly, TSP-1 has been shown to bind both CD36 and CD47, inhibiting tumour growth and modulating the TME." (PMID 41163221, 2025).
tumor (continued). "Concurrently, based on the evidence linking fatty acid and glutamine metabolism to tumor progression, therapeutic strategies targeting SLC1A5 or CD36 could be integrated with existing chemotherapy or immunotherapy to potentially enhance therapeutic efficacy." (PMID 41212437, 2025). "Currently, CD36 monoclonal antibodies have been shown to significantly inhibit tumor metastasis without side effects in oral squamous cell carcinoma models and are expected to be useful for treating CCA." (PMID 39984452, 2025). "To test this hypothesis, we used immunostaining to examine the protein expression of key factors involved in fatty acid uptake and metabolism, including CD36 and FABP4, in tumor tissues." (PMID 40526430, 2025). "CD36 attenuates angiogenesis by binding to thrombospondin-1 (TSP-1) and thereby inducing apoptosis or blocking the vascular endothelial growth factor receptor 2 pathway in tumor microvascular endothelial cells." (PMID 41011284, 2025). "Similarly, CD36 and DAB2, when carried by EVs, contribute to lipid uptake and signal transduction within the tumor stroma." (PMID 40565366, 2025). "CD36, a fatty acid transporter, facilitates the uptake of long-chain fatty acids (LCFAs) and oxidized low-density lipoprotein (Ox-LDL), playing a crucial role in lipid metabolism and serving as a significant tumor marker." (PMID 40370433, 2025). "Reductions of the fat metabolism observed in response to belzutifan treatment (inhibition of CD36-dependent uptake of fatty acids and lipid incorporation) and the triglyceride production mediated by LPCAT1 correlate clinically with a radiographic tumor regression and symptomatic recovery." (PMID 41451091, 2025). "To explore whether the AKT-mTOR pathway is involved in pitavastatin-reduced or CD36-induced cell proliferation, we determined the activation of AKT and mTOR in cells and tumor tissues." (PMID 38319449, 2024). "In addition, pitavastatin administration reduced tumor size and weight in both C57BL/6J and CD36−/− mice." (PMID 38319449, 2024). "Moreover, reports have shown that high expression of CD36 contributes to chemotherapy resistance in leukemia and correlates with poor survival of patients with AML11 as well as in lung, bladder and breast cancer." (PMID 38643249, 2024). "Blocking CD36 in CD8+ T cells effectively restored their anti-tumor activity without influencing PD-1 expression in tumor-infiltrating CD8+ lymphocytes." (PMID 39266539, 2024). "Significantly, etomoxir-treated TAMs or those isolated from CD36 KO tumors did not have a suppressive phenotype and blocked the proliferation of multiple tumor cell types in in vitro co-culture experiments." (PMID 39742252, 2024). "Within the tumour microenvironment, CD36's facilitation of fatty acid uptake by CD8 T cells triggers exacerbated lipid peroxidation and ferroptotic events, compromising the release of cytotoxic cytokines and dampening their tumour‐suppressive capacity." (PMID 39083563, 2024). "In short term survival samples, 2 stroma clusters near the tumor edge expressed high COL1A1 and POSTN consistent with myofibroblast phenotype, while two stroma clusters distal to the tumor edge expressed high COL1A1 and CD36 (peri-vascular)." (PMID 38525245, 2024). "Recent studies have shown that CD36, a pan-lipid transporter, causes ferroptosis in CD8+ T cells rather than in tumor cells in the tumor microenvironment, where ferroptosis is pro-tumorigenic rather than anti-tumorigenic." (PMID 38719806, 2024). "To evaluate whether CD36 is involved in HFD-enhanced or pitavastatin-reduced cancer, we determined CD36 expression in tumor samples or cells." (PMID 38319449, 2024). "CD36, FABP4, and ANGPTL4 were readily detectable in tumor cells by immunostaining." (PMID 39456610, 2024).